TRPV1 (transient receptor potential cation channel subfamily V member 1)
Diseases named in the same sentence as TRPV1 in open-access papers (continued):
Sharing a sentence is not in itself a finding about the gene and the disease.
atopic dermatitis (continued). "In hairless mice with induced atopic dermatitis TRPV1 antagonist PAC-14028 administered as a cream improved skin barrier functions and restored expression of epidermal differentiation markers." (PMID 31681615, 2019). "Another study using an IL-31-induced atopic dermatitis model also showed decreases in inflammation and itching in TRPV1 knockout mice." (PMID 26700618, 2016). "The ability of troxerutin to inhibit TRPV1 activation and enhance skin barrier function presents a promising therapeutic approach, not only for sensitive skin but also for conditions such as rosacea and atopic dermatitis." (PMID 41222137, 2025). "Increased expression and phosphorylation of TRPV1 has been observed in atopic dermatitis and psoriasis, where it may correlate with itch severity." (PMID 41002951, 2025). "Interestingly, TRPV1 was also expressed by eosinophils located in proximity to peripheral nerves in atopic dermatitis (AD) skin." (PMID 38339203, 2024). "Thus, mice deficient in the SP gene Tac1 and those treated with resiniferatoxin for selective removal of the TRPV1+ nociceptor show alleviated symptoms of atopic dermatitis." (PMID 37296626, 2023). "Previous studies have shown that TRPV1 is closely related to the occurrence and/or development of skin aging and various chronic inflammatory skin diseases, such as psoriasis, atopic dermatitis, rosacea, herpes zoster, allergic contact dermatitis and prurigo nodularis." (PMID 36874007, 2023). "Furthermore, TRPV1 gene overexpression was found to be positively correlated to itch intensity in patients with atopic dermatitis and psoriasis." (PMID 36613861, 2022). "Similarly, in the skin, an increase in TRPV1 sensitivity and expression of TRPV1 is found in atopic dermatitis (AD)." (PMID 33193423, 2020). "In addition to its association with histamine-dependent acute itch, increased TRPV1 expression in the skin and DRG has been reported in multiple chronic itch diseases, such as dry skin, atopic dermatitis and prurigo nodularis." (PMID 28701920, 2017). "Additionally, we observed that CD68+/TRPV1+ cells increased in human atopic dermatitis tissue." (PMID 39257398, 2024). "In models of scleroderma and atopic dermatitis, cytokines IL-4 and IL-13, produced by Th2 cells, were found to enhance the expression of TRPA1 and TRPV1." (PMID 41596464, 2026). "TRPV1 interactions have many clinical implications including irritable bowel syndrome (IBS) and abdominal pain, atopic dermatitis, airway inflammation, and potentially infantile colic." (PMID 38888338, 2024). "Aberrant expression and activation of TRPV1 have been reported to be involved in inflammatory diseases such as oral lichen planus (OLP), psoriasis, atopic dermatitis, airway inflammation, inflammatory bowel diseases (IBD), and pancreatitis." (PMID 36919561, 2023). "Semiquantitative evaluation of the density of CB2R, GPR55, TRPV1, and TRPA1 immunoreactivity in different cellular elements of the skin of dogs with atopic dermatitis (AD-dogs)." (PMID 36187821, 2022). "The TRPV1 antagonist PAC-14028 was shown to accelerate skin barrier recovery after tape stripping and in two models of atopic dermatitis." (PMID 33800730, 2021). "Although TRPV1 is also considered a potential target of evodiamine for pain perception, it is unlikely to be responsible for its anti-atopic dermatitis effects." (PMID 38672764, 2024). "TRPV1 is expressed in sensory nerves and different non-neuronal cells of the skin, implying its role in the pathology of numerous pruritic skin disorders such as psoriasis, atopic dermatitis, and Netherton syndrome." (PMID 36551194, 2022).
inflammatory bowel disease (35 papers, 2005 to 2025). A spectrum of small and large bowel inflammatory diseases of unknown etiology. "It is surprising, especially that TRPV1 was suspected to be involved in inflammatory bowel diseases that actually predispose to colon cancer development." (PMID 31681615, 2019). "Inflammatory bowel disease is associated with the upregulation of TRPV1 in the nerve fibers of the colon." (PMID 17971242, 2007). "RNA-seq analysis showed GPR68 is robustly expressed in Trpv1+ colonic nociceptors and upregulated in tissue from people with inflammatory bowel disease, consistent with reduced disease activity in DSS-treated GPR68-/- mice." (PMID 41197770, 2025). "Studies have confirmed that TRPV1 is highly expressed in rodent models of inflammatory bowel disease and UC." (PMID 38206948, 2024). "Antagonism of transient receptor potential vanniloid-1 (TRPV1) and desensitization of transient receptor potential ankyrin-1 (TRPA1) nociceptors alleviate inflammatory bowel diseases (IBD)-associated chronic pain." (PMID 36076974, 2022). "As far as human tissues are concerned, altered TRPV1 expression in nerve fibers has been demonstrated in biopsies from patients with rectal hypersensitivity or inflammatory bowel disease (IBD)." (PMID 30374305, 2018). "TRPA1 and TRPV1 expressions were investigated in human colon biopsies of healthy subjects and patients with inflammatory bowel diseases (IBD: ulcerative colitis, Crohn's disease) with quantitative PCR and immunohistochemistry." (PMID 25265225, 2014). "TrpV1 upregulation was found in colorectal samples from patients with inflammatory bowel disease and Crohn's disease, as well as in sensory fibers from patients with rectal hypersensitivity." (PMID 23097675, 2012). "A similar correlation between pain intensity and number of mucosal TRPV1-positive nerve fibers is found in patients with quiescent inflammatory bowel disease who continue to complain of abdominal pain." (PMID 21420431, 2011). "Further down the gut, TRPV1 immunoreactive colonic nerve fibres are increased in patients with active Inflammatory Bowel Disease." (PMID 27713376, 2010). "Patients diagnosed with active inflammatory bowel disease demonstrate a greatly increased TRPV1 immunoreactivity in colonic nerve fibers, suggesting an important implication of the TRPV1 antagonists in treating GI distress." (PMID 19305794, 2008). "Perhaps the best indicator for TRPV1s involvement in gut based pain comes from human patient studies which indicate increased expression or function of TRPV1 in Gastro-Oesoghageal Reflux Disease, Functional Dyspepsia, Inflammatory Bowel Disease and Irritable Bowel Syndrome." (PMID 27713376, 2010). "While direct evidence in inflammatory bowel disease is limited, studies in irritable bowel syndrome show that miR-199 upregulates TRPV1, thereby enhancing visceral pain—an effect that is plausibly relevant to IBD." (PMID 41002400, 2025). "As TRPA1 channels are present on capsaicin-sensitive sensory neurons, they have also shown involvement in inflammatory bowel disease (IBD) along with TRPV1 channels." (PMID 34912298, 2021). "For example, animal studies showed that TRPV1 activation may have anti-inflammatory activity protecting from ischemia/reperfusion injury, contrasting the inflammation-mediated damage in inflammatory bowel disease, and reducing inflammation in sepsis and allergic contact dermatitis." (PMID 30761069, 2019). "Importantly, the density of TRPV1-positive nerve fibers in the rectosigmoid colon correlates with pain severity in both patients with irritable bowel syndrome and patients with symptomatic but quiescent inflammatory bowel disease." (PMID 21420431, 2011). "In another inflammatory disease like inflammatory bowel disease curcumin have cellular targets interaction with NF‐κB, JAKs/STATs, MAPKs, TNF‐α, IL‐6, PPAR, and TRPV1." (PMID 37324924, 2023).
inflammatory bowel disease (continued). "Here, we analyzed how TRPV1 modulates T cell-mediated inflammatory responses, which include multiple sclerosis (MS), pulmonary inflammation, inflammatory skin diseases or inflammatory bowel diseases (IBD) as well as osteoarthritis (OA)." (PMID 35634308, 2022). "In fact, TRPV-1 is involved in various inflammatory conditions, such as in inflammatory bowel disease (IBD), cutaneous neurogenic inflammation, brain inflammation, allergic asthma, colitis, arthritis, hypersensitivity, chronic obstructive pulmonary disease (COPD), and autoimmune diseases." (PMID 34805220, 2021). "It has been reported that the TRPV1 function was altered in visceral hypersensitivity-related diseases, such as gastroesophageal reflux disease, gastric hypersensitivity, and inflammatory bowel disease (IBD)." (PMID 33123210, 2020). "In patients with inflammatory bowel disease (IBD), TRPV1 immunoreactivity is greatly increased in the colonic nerve fibers." (PMID 33193423, 2020). "Thus far, we know that the expression of TRPV1 in colonic nerve fibers is upregulated in patients with IBS and in patients with inflammatory bowel disease (IBD)." (PMID 31496955, 2019).
depression (34 papers, 2011 to 2026). "It is noteworthy that synaptic plasticity mediated by the TRPV1 channel is closely associated with anxiety and depression-like mood disorders, as well as cognitive deficits, including learning and memory impairments caused by neuroinflammatory damage." (PMID 41459513, 2025). "Attenuation of TRPV1 and its related molecules implicated their involvement in the pathogenesis of chronic pain and comorbidity of depression." (PMID 35341159, 2022). "Both of these receptors have displayed involvement in nociceptive responses associated with TRPV1 involvement, and they concurrently display positive tendencies in the treatment of EA for conditions of chronic pain and depression." (PMID 34068557, 2021). "Our results show that when infected mice are treated with a TRPV1 antagonist at the initial time of infection, they fail to develop chronic pelvic pain or behavioral changes associated with anxiety and depression." (PMID 29739958, 2018). "The antidepressant-like effects of TRPV1 agonists shown in the present study suggest a characteristic involvement of TRPV1 receptors in NC-induced depression-like behaviors, similar to those caused by IM." (PMID 21767384, 2011). "Against the NC-induced depression-like behavioral alterations, as well as the IM-induced depression-like behaviors, a significant "antidepressant" attenuation was caused by the TRPV1 agonists CP and OL." (PMID 21767384, 2011). "TRPV1 receptors are known to participate in pain perception, and little is known about the TRPV1-related mechanisms underlying the depression-like behavioral alterations caused by NC similar to those caused by IM." (PMID 21767384, 2011). "This convergence has prompted the development of dual FAAH/TRPV1 inhibitors which have shown dose-dependent antidepressant-like effects in rodent models of depression, underscoring the therapeutic relevance of this pathway." (PMID 40806746, 2025). "This has also been observed in TRPV1 knockout models, indicating that TRPV1 serves as a shared target involved in the development of CIP as well as depression." (PMID 37948105, 2023). "One study looked at the antidepressant effects of TRPV1 agonists and found that the administration of capsaicin and olvanil provided significant protective effects against induced depression in mice." (PMID 36902145, 2023). "Considering the large comorbidity of pain and depression, it is not surprising that there are interesting findings regarding the role of TRPV1 in depression." (PMID 35628337, 2022). "TRPV1 mRNA levels in the medial PFC of mice that underwent the learned helplessness model of depression were significantly lower than in control mice." (PMID 35628337, 2022). "Another interesting potential TRPV1 antagonist was agomelatine, a melatonin naphthalene analog used to treat depressive disorders, which had an estimated probability of binding to the channel of 80.25%." (PMID 36559057, 2022). "Clinical trials should be performed to clarity the subsequent application of TRPV1 as a treatment target for chronic pain and depression comorbidity." (PMID 32565863, 2020). "Our findings also provided initial evidence of possible dysregulation in 3 relatively novel targets for depression: ion channels TRPV1, P2RX7 and P2RY1." (PMID 24143878, 2013). "Nevertheless, based on the results that the TRPV1 agonists CP and OL attenuated the NC-induced depression-like behavioral alterations, it is possible that TRPV1 receptors contribute, at least partially, to the NC-induced "depression"." (PMID 21767384, 2011). "Additionally, evidence from mouse models demonstrates that TRPV1 modulates key neuropsychological functions, including depression, anxiety, and cognitive impairment." (PMID 41568154, 2026). "TRPV1 signaling is involved in pain‐induced and obesity‐related depression." (PMID 41399206, 2025).
depression (continued). "Like the development of post-UTI pain itself, these data suggest that TRPV1 mediates the establishment of cognitive dysfunction consistent with depression that associated with post-UTI chronic pain, but TRPV1 is dispensable for maintenance of depressive behaviors." (PMID 29739958, 2018). "However, TRPV1 may play a temporally-specific role in the development of post-UTI chronic pelvic pain and depression because the TRPV1 antagonist capsazepine reduced allodynia and NSF latency only when administered at the onset of infection." (PMID 29739958, 2018). "Therefore, we examined if post-UTI chronic pain is also associated with cognitive dysfunction in mice consistent with depression and whether TRPV1 is a potential mediator of any dysfunction." (PMID 29739958, 2018). "Later research, aimed at understanding its mechanisms in chronic migraine, overactive bladder, and depression, revealed findings such as the role of SNARE complexes in the delivery of TRPV1 to membranes and the role of afferent feedback." (PMID 39453207, 2024). "Conclusively these findings suggest that AS-induced chronic pain and depression comorbidity elicits changes in the cerebellum lobules VI, VII, VIII, which are ameliorated through the use of EA at ST36 via its action on TRPV1 and related molecular pathways." (PMID 34068557, 2021). "Besides learning and memory deficits, patients with AD are often accompanied by depression, and laboratory research has shown that TRPV1 activation may affect anxiogenic responses and depression‐related behaviors (Abdelhamid, Kovacs, Nunez, & Larson, 2014; Kasckow, Mulchahey, & Geracioti, 2004)." (PMID 32061032, 2020). "Of the 9 ion channel receptors that we examined, P2RX7, TRPV1, and P2RY1 were upregulated in female patients during a depressive episode, and P2RY1 expression was positively related to depression severity along with 2 other ion channel receptors, TRPV4 and P2RX1." (PMID 24143878, 2013). "The TRPV1 antagonist CZ by itself did not provide any significant effects against the NC- and IM-induced depression-like behavioral alterations." (PMID 21767384, 2011). "In female patients with medication refractory depression, we recently observed dysregulated gene expression during a depressive episode for three other ATP-responsive ion channels, including the purinergic receptors P2RX7 and P2RY1, and the transient vanilloid receptor TRPV1." (PMID 24826212, 2014). "In both NC and IM groups, the TRPV1 agonists capsaicin (CP) and olvanil (OL) administered intraperitoneally provided significant antidepressant-like attenuation against these behavioral alterations, whereas the TRPV1 antagonist capsazepine (CZ) did not attenuate any depression-like behaviors." (PMID 21767384, 2011).
diabetic neuropathy (31 papers, 2006 to 2025). A chronic, pathological complication associated with diabetes mellitus, where nerve damages are incurred due to diabetic microvascular injury involving small blood vessels that supply these nerves, resulting in peripheral and/or autonomic nerve dysfunction. "Aberrant expression of TRPV1 is implicated in multiple pain associated conditions including diabetic neuropathy, irritable bowel syndrome, chronic pancreatitis, vulvodynia, and TRPV3 is elevated in inflammatory skin-related conditions like psoriasis." (PMID 33671852, 2021). "Transient receptor potential (TRP) channels such as TRPA1 and TRPV1 are implicated in both the pain and neuronal damage in diabetic neuropathy." (PMID 29930087, 2018). "Modulation of the TRP channels TRPA1 and TRPV1 has been implicated in both neuronal damage and pain in diabetic neuropathy." (PMID 29930087, 2018). "While PKCβII or TRPV1 have separately been implicated in altering thermal sensitivity of nociceptive primary afferents during diabetic neuropathy, our results support a role for both in concert with each other." (PMID 27721335, 2011). "Serine/threonine protein kinase C βII isoform (PKCβII) or the pain receptor transient receptor potential vanilloid 1 (TRPV1) have been separately implicated in mediating heat hyperalgesia during inflammation or diabetic neuropathy." (PMID 27721335, 2011). "Indeed, RAGE activation is associated with enhanced TRPV1 channel gating in models of diabetic neuropathy, which could conceivably contribute to the electrophysiological effects of HMGB1 in the present study." (PMID 34621188, 2021). "TRPV1 sensitization also accelerates the onset and severity of diabetic neuropathy by amplifying pain and inflammatory signaling pathways." (PMID 41463571, 2025). "Collectively, this research delineates that Aju-I mitigates pain behaviors in the streptozotocin (STZ)-induced diabetic neuropathy model by modulating the Nrf2/Keap-1/HO-1 signaling pathway and the activity of TRPV1/TRPM8 nociceptors." (PMID 40264787, 2025). "These insights accelerate translational applications of HUCMSC-based therapies and TRPV1 modulators for diabetic neuropathy." (PMID 41346340, 2025). "To investigate the molecular mechanisms by which HUCMSCs improve diabetic neuropathy, we cocultured mouse SCs under HG conditions with HUCMSCs and analyzed the role of the TRPV1 signaling pathway in this process." (PMID 41346340, 2025). "Human studies demonstrate that TRPV1 is upregulated in painful diabetic neuropathy, with increased TRPV1-positive nerve fibers in skin biopsies correlating with heat hyperalgesia and clinical pain severity." (PMID 41463571, 2025). "Such algetic manifestations and the upregulation of spinal CB1R, CB2R, and TRPV1 channels are present in streptozotocin-induced models of diabetic neuropathy." (PMID 37745077, 2023). "Another study by determined the potential activity of 6-paradol and its derivatives to Transient Receptor potential Vanilloid 1 (TRPV1), a target receptor in Painful Diabetic Neuropathy (PDN)." (PMID 34899343, 2021). "NGF is known to control spinal SP and TRPV1, and it has been shown to be related to pain and diabetic neuropathy." (PMID 34445280, 2021). "While for many pain applications there is a focus on orally bioavailable TRPV1 antagonists, in applications for indications such as diabetic neuropathy and post-herpetic pain, topical application of high percentage capsaicin creams are a standard approach." (PMID 31446830, 2019). "It would be interesting to see if the potential role of PKCβII in sensitizing TRPV1 signaling is specific to painful diabetic neuropathy." (PMID 27721335, 2011). "In diabetic neuropathy skin, TRPV1 expressing sub- and intra-epidermal fibres were decreased, as was expression in surviving fibres." (PMID 17521436, 2007).